RUNX1T1 (RUNX1 partner transcriptional co-repressor 1)
Diseases named in the same sentence as RUNX1T1 in open-access papers (continued):
Sharing a sentence is not in itself a finding about the gene and the disease.
cancer (49 papers, 2010 to 2025). A tumor composed of atypical neoplastic, often pleomorphic cells that invade other tissues. "Regarding DNA methylation, it is worth noting that the promoter regions of BACH2, MTAP, and RUNX1T1 were hypermethylated in NII.clusterB-PNI patients compared with NII.clusterA-PNI patients.These genes act as inhibitory factors in cancer." (PMID 37563649, 2023). "Some of the most prevalent included known pediatric cancer fusions RUNX1::RUNX1T1 (15% AML participants), KMT2A::MLLT3/MLLT10 (12% AML), TCF3::PBX1 (4.4% ALL), and ETV6::RUNX1 (2.4% ALL)." (PMID 37323575, 2023). "In this article, based on its structure, the functions of RUNX1T1 in cell fate will be illustrated over hematopoiesis, nervous system, intestinal development, adipose metabolism, and carcinoma." (PMID 35902872, 2022). "RUNX1T1 mRNA is highly expressed among SCLC cell lines compared with most other types of cancers, including non–small‐cell lung cancer (NSCLC)." (PMID 33084222, 2021). "Of them, two driver genes, MSH6 and RUNX1T1, drew our attention, as they have been repeatedly reported to be involved in multiple cancer types." (PMID 29046615, 2017). "In addition, RUNX1T1 plays wide-ranging and diverse roles in carcinoma as a biomarker, suppressor, or positive regulator of carcinogenesis, closely correlated to specific organs and dominant signaling pathways." (PMID 35902872, 2022). "To determine whether RUNX1T1 expression was higher in general in SCLC compared with NSCLC and other cancers, we initially looked at the expression profile of RUNX1T1 mRNA using the Broad Cancer Cell Line Encyclopedia (CCLE) database." (PMID 33084222, 2021). "Notably, two trunk genes (SPEN and ITK), a branch gene (SMARCE1), and several private genes (FAT4, CACNA1D, ATR, RUNX1T1, TERT, and SRGAP3) were defined as cancer-associated genes, according to the cancer gene census." (PMID 28716121, 2017). "Based on our findings, we hypothesized that RUNX1T1 also plays a role in other MYC-driven cancers." (PMID 38992040, 2024). "We find that RUNX1/RUNX1T1 controls RNA-isoform expression by preventing alternative initiation of transcription and, thus, directly link an initiating and driving oncogenic event with the recently discovered pervasive regulation of transcription through alternative promoters in cancer cells." (PMID 33483506, 2021). "Moreover, RAD51 could impede the repair of genes, and RUNX1T1 might block the differentiation of cancer cells." (PMID 27484176, 2016). "Mutations in RUNX1T1 (encoding cyclin-D-related protein, a transcriptional regulator) and WDR17 (WD repeat-containing protein 17) were identified in 3 patient samples in the cohort and predicted to be likely cancer driver mutations impacting protein function by all 4 algorithms." (PMID 26536348, 2015). "Among these, we identify a number of known cancer genes (i.e., FOXL2, RUNX1T1), transcription factors (i.e., MEIS2), as well as LHX1 and PAX6 (which are also recurrently affected by mutations)." (PMID 33741928, 2021). "Moreover, there is existing literature demonstrating the important roles of ABI3BP, WASF2, RUNX1T1, and TNFAIP8L2 in cancer processes through pan-cancer analysis." (PMID 37942289, 2023). "Additionally, the gene targets of these miRNAs included several cancer driver genes including ZNF704 (targeted by ten miRNAs), MMP16 (targeted by eight miRNAs), and KCNN3, POU2F1, ADARB1, MPZL1, RUNX1T1, UBE2W, and DYRK1A genes (targeted by seven miRNAs)." (PMID 37685851, 2023). "Despite extensive efforts to understand the function of Runx1t1 protein in the etiology of cancer, the lack of knowledge about their function in normal embryonic development continues to persist." (PMID 32321587, 2020). "Although not previously shown to be directly related with cancers, several surface markers, such as CD19 and CD34, showed significant positive correlation (Pearson R > 0.5) with RUNX1T1 in RNA levels, whereas CD33 showed negative correlation (Pearson R = −0.36)." (PMID 30959925, 2019).
hematological malignancies (3 papers, 2021 to 2024). "The RUNX1T1 gene, encoding for a transcriptional co-repressor, is involved in hematological disorders via chromosomal rearrangements." (PMID 39478125, 2024).
CNS tumor (2 papers, 2020 to 2025). "Researchers considered RUNX1T1 as a prognostic biomarker for CNS tumors." (PMID 32266223, 2020).
infection (2 papers, 2019 to 2025). The state of being infected such as from the introduction of a foreign agent such as serum, vaccine, antigenic substance or organism. "PA infection causes downregulation of Hist1h2bc and Runx1t1 genes." (PMID 31842752, 2019).
RUNX1T1 also shares sentences with these, for which no sentence is quoted: chronic myeloid leukemia (7 papers); Myelodysplasia (6); blood cancers (5); myelodysplastic syndrome (5); acute lymphoblastic leukemia (4); eosinophilia (3); Ewing sarcoma (3); lymphoid neoplasm (3); mastocytosis (3); prostate carcinoma (3); systemic mastocytosis (3); acute megakaryoblastic leukemia (2); anemia (2); cardiovascular disease (2); myeloid neoplasm (2); pancreatic cancer (2); Splenomegaly (2); Wilms tumor (2); Abdominal obesity (1); acute erythroid leukemia (1); acute GVHD (1); Acute myelomonocytic leukemia (1); adenocarcinoma of (1); allergic contact dermatitis (1); alveolar rhabdomyosarcoma (1); aplastic anaemia (1); B-cell acute lymphoblastic leukemia (1); brain disease (1); carcinoid (1); chronic myelomonocytic leukemia (1).
A further 34 diseases each share a sentence with RUNX1T1 in 1 paper.